Y_RNA (Y RNA )
Gene: Miscellaneous RNA gene on chromosome 10 (73,082,494 to 73,082,595, reverse strand). Ensembl gene ENSG00000201047.
Homologues: Orthologues: chimpanzee Y_RNA (100% identical). Paralogues in human: Y_RNA (87% identical), Y_RNA (86% identical), RNY3 (85% identical), Y_RNA (85% identical), RNY3P14 (84% identical), Y_RNA (84% identical), Y_RNA (83% identical), RNY3P1 (82% identical), RNY3P16 (82% identical), Y_RNA (82% identical), RNY3P2 (81% identical), Y_RNA (81% identical), and 93 more.